WDR44 (WD repeat domain 44)
Description:
Downstream effector for Rab11 which regulates Rab11 intracellular membrane trafficking functions such as endocytic recycling, intracellular ciliogenesis and protein export. ATK1-mediated phosphorylation of WDR44 induces binding to Rab11 which activates endocytic recycling of transferrin receptor back to the plasma membrane. When bound to Rab11, prevents the formation of the ciliogenic Rab11-Rabin8/RAB3IP-RAB11FIP3 complex, therefore inhibiting preciliary trafficking and ciliogenesis. Participates in neo-synthesized protein export by connecting the endoplasmic reticulum (ER) with the endosomal tubule via direct interactions with the integral ER proteins VAPA or VAPB and the endosomal protein GRAFs (GRAF1/ARHGAP26 or GRAF2/ARHGAP10), which facilitates the transfer of proteins such as E-cadherin, MPP14 and CFTR into a Rab8-Rab10-Rab11-dependent export route.
Synonyms: Rab11BP; RPH11; DKFZp686L20145; SYM-4
Tractability: Antibody: UniProt places it where antibodies can reach, with high confidence. PROTAC: ubiquitination databases record sites on it; its protein half-life has been measured.
Gene: Protein-coding gene on chromosome X (118,345,968 to 118,450,285, forward strand). Ensembl gene ENSG00000131725.
Subcellular location: Cytoplasm, cytosol; Cytoplasm, perinuclear region; Endosome membrane; Golgi apparatus, trans-Golgi network
Subcellular location (Human Protein Atlas): Golgi apparatus
Gene Ontology:
Molecular function: molecular sequestering activity; protein binding; small GTPase binding
Biological process: cytosolic ciliogenesis; negative regulation of cilium assembly; regulation of vesicle-mediated transport
Cellular component: endosome membrane; Golgi apparatus; cytosol; perinuclear region of cytoplasm
Homologues: Orthologues: chimpanzee WDR44 (100% identical), macaque WDR44 (98% identical), dog WDR44 (94% identical), rabbit WDR44 (93% identical), mouse Wdr44 (92% identical), rat Wdr44 (92% identical), guinea pig WDR44 (92% identical), pig WDR44 (91% identical), zebrafish wdr44 (67% identical), Drosophila melanogaster CG34133 (44% identical), Caenorhabditis elegans sym-4 (35% identical).
Diseases named in the same sentence as WDR44 in open-access papers:
WDR44 is named in the same sentence as 5 diseases in open-access papers, as found by Europe PMC text mining. Sharing a sentence is not in itself a finding about the gene and the disease. The quoted sentences say what the papers report.
ciliopathy (1 paper, 2024). A genetic disorder of the cellular cilia or the cilia anchoring structures, the basal bodies, or of ciliary function. "In the present study, we describe a novel pleotropic developmental disorder associated with ciliopathy-related features due to X-linked WDR44 variants." (PMID 38191484, 2024). "Overall, our clinical and experimental findings support WDR44 variants as the cause of a pleiotropic disorder in eight of nine cohort families involving many of the organ systems typically affected in ciliopathies through a cilia-linked mechanism." (PMID 38191484, 2024). "Here, we describe male patients with missense and nonsense variants within the WD40 repeats (WDR) of WDR44, an X-linked gene product, who display ciliopathy-related developmental phenotypes that we can model in zebrafish." (PMID 38191484, 2024). "Ciliopathy associated congenital heart defects were also observed in three of our patients, and heart edema was observed in zebrafish embryos expressing WDR44 variants." (PMID 38191484, 2024). "Indeed, our observation that more severe ciliopathy-associated WDR44 variants show stronger association with enlarged RAB11 membrane compartments supports this theory." (PMID 38191484, 2024). "This observed WDR44-related disorder might therefore belong to the continuously expanding list of second-order ciliopathies, i.e., diseases that are caused by pathogenic variants in genes encoding protein that are not localized within cilia but that have a role in cilium formation and function." (PMID 38191484, 2024). "To determine if we can model WDR44 ciliopathy-related disease, we used zebrafish for functional studies after expressing the human variants." (PMID 38191484, 2024). "While our studies support a GOF mechanism, we cannot rule out that loss of function (LOF) of WDR44 contributes to the ciliopathy-like phenotype observed, because protein expression data was only available for a limited number of patients." (PMID 38191484, 2024). "In conclusion, our study unveils a novel pleiotropic developmental disorder due to WDR44 variants resulting in a ciliopathy spectrum associated with impaired ciliogenesis initiation, and possibly a more complex disease that also affects non-ciliary related WDR44 function." (PMID 38191484, 2024).
cancer (1 paper, 2022). A tumor composed of atypical neoplastic, often pleomorphic cells that invade other tissues. "Second, the proposed approach also enables identification and exploration of driver genes; our analyses implicate DMD, RSK4, OFD1, WDR44, and AFF2 as potential cancer drivers." (PMID 35753349, 2022).
WDR44 also shares sentences with these, for which no sentence is quoted: infection (1 paper); Renal cyst (1); Talipes equinovarus (1).